TSLP (thymic stromal lymphopoietin)
Diseases named in the same sentence as TSLP in open-access papers (continued):
Sharing a sentence is not in itself a finding about the gene and the disease.
acute coronary syndrome (1 paper, 2015). Signs and symptoms related to acute ischemia of the myocardium secondary to coronary artery disease. "Abnormal expression of thymic stromal lymphopoietin (TSLP) and its receptor (TSLPR) was found in patients with acute coronary syndrome." (PMID 26517374, 2015).
acute sinusitis (1 paper, 2023). "These 56 phenotypes include infectious and inflammatory disorders of the upper respiratory tract that were not included in our definition of IURD: acute sinusitis (9p24.1 near IL33 and 17q21.1 near IKZF3) and acute respiratory infections (5q22.1 near TSLP/WDR and 9p24.1 near IL33)." (PMID 36653354, 2023).
African trypanosomiasis (1 paper, 2017). "Although the role of TSLP in immunity has been well studied in allergic diseases, its role in resistance to parasitic diseases including African trypanosomiasis is still poorly defined." (PMID 28769924, 2017). "Although susceptibility to experimental Trypanosoma congolense infection in mice is associated with excessive proinflammatory responses due in part to impaired Th2 response, the role of TSLP in resistance to African trypanosomiasis has not been well studied." (PMID 28769924, 2017).
AIDS (1 paper, 2023). A syndrome resulting from the acquired deficiency of cellular immunity caused by the human immunodeficiency virus (HIV). "Thymic stromal lymphopoietin (TSLP) activates intracellular JAK/STAT, PI3K pathways by binding to receptor TSLPR and mediates the production of inflammatory factors IL-23, IL-17, and IL-4, which may be involved in the pathogenesis of inflammatory AIDs." (PMID 37859999, 2023).
allergic bronchopulmonary aspergillosis (1 paper, 2025). Allergic bronchopulmonary aspergillosis (ABPA) is a rare immunologic pulmonary disorder caused by hypersensitivity to Aspergillus fumigatus, clinically manifesting with poorly controlled asthma and recurrent pulmonary infiltrates. "In mucus-predominant allergic bronchopulmonary aspergillosis/ABPM with high FeNO/IgE levels after anti-IL-5 therapy, phenotype- and biomarker-guided sequencing of anti-TSLP antibodies may be considered." (PMID 41487819, 2025).
autoimmune gastritis (1 paper, 2025). Inflammation of the body fundic mucosa of the stomach. "TSLP is an epithelial-derived cytokine that regulates immune tolerance, and its dysregulation has been implicated in various human autoimmune diseases, making this pathway relevant to understanding autoimmune gastritis pathogenesis." (PMID 40673273, 2025). "This accelerated disease progression in TSLP-deficient mice demonstrates the critical role of epithelial-immune cell communication in maintaining gastric tolerance, which may be disrupted in human autoimmune gastritis." (PMID 40673273, 2025).
benign breast tumors (1 paper, 2019). "In addition, malignant or cancerous tumors presented higher levels of TSLP than benign breast tumors." (PMID 31210014, 2019).
blood disease (1 paper, 2008). A disease that occurs in the blood. "Infection is the most likely cause of granulocytosis in the mutant animals; however, it is intriguing to speculate that persistently high levels of TSLP also contribute to this blood disease (and Dr. Freddy Radtke, personal communication)." (PMID 18507503, 2008).
chronic granulomatous disease (1 paper, 2019). Chronic granulomatous disease (CGD) is a rare primary immunodeficiency, mainly affecting phagocytes, which is characterized by an increased susceptibility to severe and recurrent bacterial and fungal infections, along with the development of granulomas. "Chronic granulomatous disease (CGD) patients possess mutations in genes encoding proteins that form the nicotinamide adenine dinucleotide phosphate-oxidase (NADPH) complex; thus these patients are unable to generate NADPH oxidase-derived ROS and TSLP from mDC in response to dectin-1 agonists." (PMID 31139177, 2019).
chronic tonsillitis (1 paper, 2017). "We observed increased expression of TSLP in tonsillar GCs of IgAN patients compared to IgAN patients with TW treatment and non-IgAN chronic tonsillitis, and there was a positive correlation between IgA and TSLP expression levels in tonsils (R = 0.768, and P < 0.05 for Spearman’s correlation)." (PMID 29312588, 2017).
coagulopathy (1 paper, 2023). "Patients with fatal outcomes presented increased levels of interferon-λ, TGF-α, thymic stromal lymphopoietin (TSLP), IL-16, IL-23, and IL-33, and markers linked to coagulopathy, such as thrombopoietin." (PMID 37376587, 2023).
colon adenoma (1 paper, 2016). An adenoma that arises from the colon. "Interestingly, we found that TSLP mRNA expression significantly decreased in colon adenomas." (PMID 26919238, 2016).
cutaneous leishmaniasis (1 paper, 2023). Leishmaniasis affecting the skin. "To identify the source of TSLP during cutaneous leishmaniasis, we sorted CD45+ hematopoietic and CD45- nonhematopoietic cells from the ears of either naïve or infected WT and eoCre: Il4/13f/f mice having a selective deficiency of IL-4/IL-13 in eosinophils." (PMID 38030609, 2023). "In summary, we demonstrate that dermal TRMs orchestrate localized type 2 circuitries with ILC2s and eosinophils, mediated by TSLP and CCL24 respectively, to promote non-healing cutaneous leishmaniasis." (PMID 38030609, 2023). "Here Lee and colleagues show dermis-resident macrophages are a source of thymic stromal lymphopoietin and CCL24, which act on type 2 innate lymphoid cells and eosinophils respectively, to maintain their M2 properties and promote non-healing cutaneous leishmaniasis." (PMID 38030609, 2023).
cutaneous melanoma (1 paper, 2022). A primary melanoma arising from atypical melanocytes in the skin. "Further exploration of TSLP induction signals in tumor contexts, including recently reported tumor-derived extracellular vesicles, is needed to identify new strategies for the modulating inflammatory microenvironment associated with cutaneous melanoma." (PMID 36107619, 2022). "Here, we show that expression of the cytokine thymic stromal lymphopoietin (TSLP) by epidermal keratinocytes is induced by cutaneous melanoma in both mice and humans." (PMID 36107619, 2022). "Our study provides insights into the role of TSLP in programming a protumoral immune microenvironment in cutaneous melanoma." (PMID 36107619, 2022). "We next examined whether GATA3+ Tregs accumulated at cutaneous melanoma sites in Braf/Pten mice and whether this was dependent on TSLP." (PMID 36107619, 2022). "In agreement with this, we did not detect TSLP expression in malignant cells, immune cells, or stromal cells in published single-cell RNA-Seq (scRNA-Seq) data sets for human cutaneous melanoma." (PMID 36107619, 2022).
cutaneous sarcoidosis (1 paper, 2022). "Thus far, no studies have investigated TSLP expressed in LP and cutaneous sarcoidosis." (PMID 36046760, 2022).
cutaneous squamous cell carcinoma (1 paper, 2022). "It has also been shown that TSLP can recruit IgE-bearing basophils into inflamed skin, and IgE promotes inflammation-driven tumor growth during chronic tissue inflammation in a cutaneous squamous cell carcinoma model." (PMID 35432341, 2022).
cyst (1 paper, 2022). A sac-like closed membranous structure that may be empty or contain fluid or amorphous material. "Probiotic and prebiotic treatments diminished the production of TSLP, cyst-LTs, LTC4, LTB4, GTP, and GOT which lead to control of inflammation in airways and harnessing of immune-inflammatory responses in lung and could control bronchial inflammo-pathology." (PMID 35296330, 2022).
disc degeneration (1 paper, 2020). "Considering the pivotal role of TWEAK and TSLP we review our current understanding of these factors and their involvement in disc degeneration." (PMID 32211586, 2020).
dry eyes (1 paper, 2022). "Increases of IFN-γ, IL-2, IL-4, IL-5, IL-13 or IL-β1 in SAC; TSLP in both PAC and SAC; and IL-17, IL-21 and IL-22 in dry eyes have been observed in different studies." (PMID 35935953, 2022).
endometrial tumours (1 paper, 2021). "We uncovered that the short-form TSLP (sfTSLP) was predominantly expressed by human ovarian and endometrial tumours and overexpressing the sfTSLP in cancer cells resulted in tumour growth in vitro." (PMID 33652749, 2021).
fungal infections (1 paper, 2018). "In the cases of allergen exposure, parasitic, viral, and fungal infections, and wound repair, damaged or stimulated lung epithelial cells of the airways and alveoli, as well as blood vessel endothelial cells, produce and release IL-33, IL-25, and thymic stromal lymphopoietin (TSLP) locally." (PMID 29872441, 2018).
hearing loss (1 paper, 2024). "This study investigated the causal relationships between various inflammatory proteins (including CCL19, CDCP1, and TSLP) and multiple types of hearing loss (SNHL, SIHL, and OHL)." (PMID 39677857, 2024).
heart failure (1 paper, 2024). Inability of the heart to pump blood at an adequate rate to meet tissue metabolic requirements. "Our findings suggest that TSLP may play a pivotal immunomodulatory role in post-MI heart failure, hinting at its potential as a therapeutic option for patients." (PMID 39703503, 2024). "Collectively, our data indicate a critical role for TSLP in facilitating cardiac repair and conferring protection against MI, primarily through regulating CD4+ T cell responses, which may provide a potential novel therapeutic approach for managing heart failure after MI." (PMID 39703503, 2024).
interstitial lung disease (1 paper, 2017). A diverse group of lung diseases that affect the lung parenchyma. "Beyond this work, few studies have attempted to address the clinical relevance of IL-33 and TSLP expression in the context of IPF or other interstitial lung diseases." (PMID 28202030, 2017). "Cut-off values of 4.66 pg/μg TSLP and 2.52 pg/μg IL-33 possessed 99.4 and 93.2% accuracy for differentiating among the IPF and other interstitial lung disease groups." (PMID 28202030, 2017). "The ROC curves for TSLP and IL-33 demonstrated a clear difference between the IPF and NC groups (TSLP: AUC = 0.655; IL33: AUC = 0.706), as well as among the patients with IPF and those with other interstitial lung diseases (n = 61, TSLP: AUC = 0.786, and IL-33: AUC = 0.781)." (PMID 28202030, 2017).
intestinal inflammation (1 paper, 2017). "By promoting the secretion of thymic stromal lymphopoietin, epidermal growth factor, IL-10, IL-25, and transforming growth factor-β1 by intestinal epithelial cells, Gal1 can inhibit experimental intestinal inflammation." (PMID 28086216, 2017).
irritant dermatitis (1 paper, 2025). An inflammatory skin condition caused by direct contact between the skin and an irritating substance. "In atopic and irritant dermatitis models, topical BCP suppresses keratinocyte interleukin-4 (IL-4)–driven thymic stromal lymphopoietin (TSLP) signaling and improves lesion severity." (PMID 41304852, 2025).
Kawasaki Syndrome (1 paper, 2022). "TSLP expression is activated by cytokines including IL-4, IL-1 and TNF-α 53, and high TSLP expression appears to play a role in platelet activation and thrombosis in Kawasaki disease 54, as well as in the metabolic syndrome and high blood pressure of severely obese individuals 52-55." (PMID 36313221, 2022).
keratitis (1 paper, 2026). A corneal disease that is characterized by inflammation of the cornea. "IL-4 has also been shown to enhance TSLP expression in a mouse model of keratitis induced by Aspergillus fumigatus." (PMID 41576028, 2026).
low grade glioma (1 paper, 2024). A grade I or grade II glioma arising from the central nervous system. "In addition, results show an association between TSLP expression levels and neutrophil infiltration in GBM but not in low-grade glioma (LGG), as indicated by a significant positive correlation (Rho: 0.184, p < 0.0318)." (PMID 38557942, 2024).
lumbar disc degeneration (1 paper, 2017). "This study aims to investigate the role of thymic stromal lymphopoietin (TSLP) in the pathogenesis of lumbar disc degeneration (LDD)." (PMID 28746197, 2017).
lupus nephritis (1 paper, 2023). Glomerulonephritis in the context of systemic lupus erythematosus. "On the other hand, basophils have been reported to play a role in the pathogenesis of lupus nephritis via the activation of autoreactive IgE, thymic stromal lymphopoietin, or Toll-like receptors (TLRs)." (PMID 36824606, 2023).
lymph node metastases (1 paper, 2019). "In addition, the correlation of TSLP overexpression with various clinicopathological factors, such as pathological differentiation, FIGO stage, pelvic, and lymph node metastases, was found." (PMID 31023965, 2019).
malaria (1 paper, 2023). Malaria is a serious and sometimes fatal disease caused by a parasite that commonly infects a certain type of mosquito which feeds on humans. "Outside of pregnancy, expression of TSLP in PBMCs was higher in asymptomatic patients with malaria compared to severe cases." (PMID 37634385, 2023). "Given the higher gene expression of TSLP observed in parasitemic, primigravid women, and the documented role of TSLP in CD4+ T cell differentiation, we next investigated differences in malaria-specific CD4+ T cell subsets and response." (PMID 37634385, 2023).
necrotizing enterocolitis (1 paper, 2025). Necrotizing enterocolitis (NEC) is a devastating disease that affects mostly the intestine of premature infants. "Although this research focused on necrotizing enterocolitis (NEC), the PI3K-Akt and NF-κB pathways are likewise crucial regulators of TSLP expression." (PMID 40861437, 2025).
nematode infection (1 paper, 2024). "The production of IL-4 and IL-13 during nematode infection in vivo is mainly initiated by the alarmins IL-25, IL-33 and TSLP released by epithelial and stromal cells." (PMID 38414039, 2024).
Osteopenia (1 paper, 2010). Osteopenia is a term to define bone density that is not normal but also not as low as osteoporosis. "Furthermore, RXRs mutant mice do not develop a fatal MPD or osteopenia, presumably because of the lower (10-15 x) TSLP serum levels." (PMID 20174635, 2010).
pancreatic adenocarcinoma (1 paper, 2022). "In pancreatic adenocarcinoma, PYCARD secreted by tumor cells and tumor-associated macrophages (TAMs) stimulated thymic stromal lymphopoietin (TSLP) secretion of fibroblasts in the TME, and high PYCARD and TSLP expressions were linked to worse prognosis." (PMID 36291776, 2022).
periodontal disease (1 paper, 2024). "Studies showed that alginate hydrogel loaded with the thymic stromal lymphopoietin (TSLP) and granulocyte‐macrophage colony‐stimulating factor (GM‐CSF) could upregulate the DC and FOXP3+ cells' number, which would hold promise to treat the upregulated pathologic inflammation of periodontal disease." (PMID 39420948, 2024).
peripheral nerve injury (1 paper, 2023). Injury to a peripheral nerve. "In this study, TSLP inhibition effectively prevented the development of neuropathic pain and increased the number of T cells after peripheral nerve injury." (PMID 37660072, 2023).
polyposis (1 paper, 2016). "In conclusion, we have shown that poly(I:C)-induces expression of TSLP in primary nasal epithelial cells from polyposis patients only and that a deregulation of the expression of the DUSP-1 transcription factor may play a role in this process." (PMID 27050744, 2016).
proliferative glomerulonephritis (1 paper, 2015). A constellation of renal disorders characterized by an increase number of cells in the glomerulus; these disorders generally present with nephrotic syndrome, and generally progress to end stage renal failure over a matter of weeks to years, depending on the etiology. "We have already mentioned in the Introduction that TSLP transgenic mice often develop mixed cryoglobulins and cryoglobulinemic type I membrano-proliferative glomerulonephritis as well as additional features that closely resemble important aspects of the human disease." (PMID 25889007, 2015).
pulmonary sarcoidosis (1 paper, 2022). Sarcoidosis affecting the lung parenchyma. "Previous studies have shown that the TSLP level in the bronchoalveolar lavage fluid of pulmonary sarcoidosis is not higher than that of normal controls." (PMID 36046760, 2022).
RSV bronchiolitis (1 paper, 2025). "Studies have shown that variants in genes such as IL-33, TSLP, and CCL5 exhibit differential expression in epithelial and immune cell subpopulations, further supporting their mechanistic role in driving persistent airway inflammation and remodeling after RSV bronchiolitis." (PMID 40872787, 2025).
Sm (1 paper, 2019). "Furthermore, a recent study showed that IL-33 needs to synergize with two other cytokine alarmins, thymic stromal lymphopoietin (TSLP) and IL-25, to induce IL-4/IL-13-dependent inflammation and fibrosis after Sm infection." (PMID 31200771, 2019).
ST Elevation Myocardial Infarction (1 paper, 2022). A myocardial infarction that produces elevation in the ST segments of the ECG. "The non-ST-elevation myocardial infarction (NSTEMI) group had slightly higher plasma levels of TSLP than the ST-elevation myocardial infarction (STEMI) group [12.01 (8.56–17.28) pg/mL vs. 10.4 (7.28–13.61) pg/mL], without significant difference (p = 0.248)." (PMID 35321112, 2022).
staphylococcus aureus infection (1 paper, 2021). An infectious process in which the bacteria Staphylococcus aureus is present. "Staphylococcus aureus infection induced significant elevation in TSLP level (p < 0.05)." (PMID 33828484, 2021).
thymic atrophy (1 paper, 2010). "Keratinocyte growth factor (KGF) and thymic stromal lymphopoietin (TSLP), which is known to stimulate thymus stromal cells, can promote thymopoiesis in mice following chemotherapy-induced thymic atrophy." (PMID 20546588, 2010).
Trichinella spiralis infection (1 paper, 2023). "After Trichinella spiralis infection, basophils have been shown to be rapidly recruited systematically by thymic stromal lymphopoietin (TSLP)-dependent mechanisms." (PMID 37325618, 2023).
unstable angina (1 paper, 2024). "Recently, a clinical study revealed that patients with acute MI have higher plasma TSLP concentrations than those with unstable angina (UA)." (PMID 39703503, 2024).
vasculitis (1 paper, 2015). "Overall, this study shows that TSLP secreted by hepatocytes and keratinocytes of HCV-infected patients with CV is involved in the pathogenesis of vasculitis and may possibly support the therapeutic use of TSLP-targeted monoclonal antibodies." (PMID 25889007, 2015). "Cutaneous expression of TSLP by the keratinocytes of patients with HCV-related CV may be pivotal in perpetuating the activation of tissue-resident immunocytes and in attracting inflammatory cells, thus creating an environment favorable to the onset of vasculitis." (PMID 25889007, 2015).